IGLV1-36 (immunoglobulin lambda variable 1-36)
Description:
V region of the variable domain of immunoglobulin light chains that participates in the antigen recognition. Immunoglobulins, also known as antibodies, are membrane-bound or secreted glycoproteins produced by B lymphocytes. In the recognition phase of humoral immunity, the membrane-bound immunoglobulins serve as receptors which, upon binding of a specific antigen, trigger the clonal expansion and differentiation of B lymphocytes into immunoglobulins-secreting plasma cells. Secreted immunoglobulins mediate the effector phase of humoral immunity, which results in the elimination of bound antigens. The antigen binding site is formed by the variable domain of one heavy chain, together with that of its associated light chain. Thus, each immunoglobulin has two antigen binding sites with remarkable affinity for a particular antigen. The variable domains are assembled by a process called V-(D)-J rearrangement and can then be subjected to somatic hypermutations which, after exposure to antigen and selection, allow affinity maturation for a particular antigen.
Synonyms: IGLV136; V1-11
Gene: Immunoglobulin variable (V) gene on chromosome 22 (22,431,958 to 22,432,465, forward strand). Ensembl gene ENSG00000211655.
Subcellular location: Secreted; Cell membrane
Gene Ontology:
Biological process: immune response
Cellular component: extracellular region; immunoglobulin complex; plasma membrane
Homologues: Paralogues in human: IGLV1-44 (85% identical), IGLV1-47 (83% identical), IGLV1-40 (78% identical), IGLV1-51 (75% identical), IGLV1-50 (74% identical), IGLV2-18 (65% identical), IGLV2-14 (64% identical), IGLV2-11 (63% identical), IGLV2-23 (63% identical), IGLV2-8 (63% identical), IGLV6-57 (62% identical), IGLV2-33 (57% identical), and 81 more.
Diseases named in the same sentence as IGLV1-36 in open-access papers:
IGLV1-36 is named in the same sentence as 3 diseases in open-access papers, as found by Europe PMC text mining. Sharing a sentence is not in itself a finding about the gene and the disease. The quoted sentences say what the papers report.
monoclonal gammopathy (1 paper, 2022). A condition characterized by the abnormal presence of monoclonal immunoglobulins in the blood or urine. "For example, IGLV1-36 gene is a potentially therapeutic option for POEMS (polyneuropathy, organomegaly, endocrinopathy, monoclonal gammopathy, and skin changes) syndrome." (PMID 36146599, 2022).
IGLV1-36 also shares sentences with these, for which no sentence is quoted: endocrinopathy (1 paper); polyneuropathy (1).